DUX4 (double homeobox 4)
Diseases named in the same sentence as DUX4 in open-access papers (continued):
Sharing a sentence is not in itself a finding about the gene and the disease.
sarcoma (continued). "Of note, in one CIC::DUX4 translocated sarcoma (CDS#2) and in three OS (OS#2, OS#5, OS#6) patients, two different tissue samples, taken in different stages of the progression of the disease, were available." (PMID 41514647, 2025). "CIC::DUX4 sarcoma is an aggressive subtype of undifferentiated small round cell sarcoma, characterized by an oncogenic fusion between the capicua (CIC) gene and the double homeobox 4 gene (DUX4)." (PMID 40760094, 2025). "Of the 12 CNS tumors with various CIC fusion partners, nine cases clustered with the reference MC: CIC-rearranged sarcoma, alongside 2 peripheral sarcomas with CIC::DUX4 gene fusion, serving as internal controls." (PMID 38926750, 2024). "Although the CIC::DUX4 fusion was the first CIC-rearranged sarcoma identified in 2006, there are still inadequate chemotherapy regimens utilized for CDS." (PMID 38882060, 2024). "Eventually, Kondo and colleagues established NCC-CDS2-C1 patient-derived cell lines using a surgically resected tumor tissue from another patient with CIC::DUX4 sarcoma (CDS) containing a similar CIC::DUX4 fusion transcript." (PMID 38882060, 2024). "Xenografts and cell lines derived from patients with CIC::DUX4-driven sarcomas have hyperactivation of the PI3K/AKT pathway through autocrine signaling by high-mobility group A (HMGA) and insulin-like growth factor (IGF) proteins." (PMID 38916046, 2024). "Along these lines, different HOX family members were found among the most upregulated genes in a BCOR::MAML3 sarcoma when compared to Ewing sarcoma with EWSR1::FLI1 fusions and CIC::DUX4 positive sarcomas." (PMID 38611033, 2024). "Round cell sarcomas with BCOR alterations usually harbor BCOR::CCNB3 and BCOR::MAML3 genetic fusions, and CIC-rearranged sarcomas are characterized by CIC::DUX4 chimeric transcript." (PMID 39021466, 2024). "To broaden our findings beyond transient expression systems and 293T cells, we next aimed to stably express CIC::DUX4 or the C1-deleted mutant in cell lines more reflective of sarcoma biology." (PMID 39530749, 2024). "We show in mammalian settings that the capicua C1 functional domain is a supercharger for CIC::DUX4, a poorly studied fusion oncoprotein which drives a rare sarcoma with dismal outcomes." (PMID 39530749, 2024). "We chose to employ mouse NIH/3T3 fibroblasts and mouse C2C12 myoblasts, as both have previously been used to study CIC::DUX4 and other sarcomas and represent the putative progenitor of soft tissue sarcomas (mesenchymal lineage—myoblast)." (PMID 39530749, 2024). "“CIC fused sarcoma” group consisted of CIC::DUX4 (n = 22), CIC break (FISH) (n = 7) and ATXN1::NUTM1 (n = 2)." (PMID 37212486, 2023). "Immunohistochemically, DUX4 is a highly sensitive and specific marker for the differentiation of sarcoma with CIC::DUX4 fusion from its histologic mimics." (PMID 36983010, 2023). "The suppression of IFNγ signaling by endogenous DUX4 in FSHD muscle cells and the CIC-DUX4 fusion protein in sarcomas provides support for the biological relevance of these findings." (PMID 37092726, 2023). "CIC-DUX4 sarcoma (CDS) is a rare but highly aggressive undifferentiated small round cell sarcoma driven by a fusion between the tumor suppressor Capicua (CIC) and DUX4." (PMID 37808628, 2023). "DUX4 rearrangements have been identified in specific types of pediatric B cell acute lymphoblastic leukemia, in small round cell bone and soft tissue sarcomas – the so-called CIC-DUX4 rearranged family of sarcomas, and rhabdomyosarcoma." (PMID 36741019, 2023). "Endogenous DUX4 suppresses interferon-stimulated gene (ISG) induction in a sarcoma cell line expressing a CIC-DUX4 fusion gene." (PMID 37092726, 2023). "Capicua–double homeobox 4 (CIC-DUX4) rearranged sarcoma (CDS) is a subcategory of small round blue cell tumors defined by the presence of the oncogenic driver CIC-DUX4 hybrid protein." (PMID 34903601, 2022).
sarcoma (continued). "Capicua-double homeobox 4 (CIC-DUX4)–rearranged sarcomas (CDS) are extremely rare, highly aggressive primary sarcomas that represent a major therapeutic challenge." (PMID 34903601, 2022). "While in most peripheral CIC‐rearranged sarcomas the fusion partner is DUX4, in the brain the most common fusion partner is NUTM1." (PMID 35266242, 2022). "DUX4 is also translocated, giving rise to chimeric oncogenic proteins at the basis of sarcoma and leukemia forms." (PMID 34943834, 2021). "A fusion between CIC and a transcription activator domain of double homeobox 4 (DUX4) (CIC–DUX4 fusion protein) was identified in Ewing-like sarcoma cells." (PMID 32238859, 2020). "The detrimental effect of DUX4 on myogenesis and terminal differentiation is further corroborated by different types of cancer, specifically fusion sarcomas, where nuclear DUX4 expression is considered a promising histochemical marker." (PMID 33067535, 2020). "Using our published chromatin profiling studies (Chromatin immunoprecipitation followed by sequencing, ChIP-Seq) from patient-derived CIC::DUX4 fusion positive sarcoma cells (NCC_CDS1_X1_C1), we identified 392 high-confidence targets (FDR q < 0.001) that overlap with CIC binding peaks." (PMID 40760094, 2025). "Thus, similar to other cancers, WEE1 expression in CIC::DUX4 sarcoma provides a molecular break that delays cell-cycle progression under high replicative stress states to enable effective DNA repair prior to mitosis." (PMID 40760094, 2025). "The occurrence of DUX4 rearrangements among these sarcoma subtypes may indicate that DUX4 could have an oncogenic potential that is specific to this stem cell type." (PMID 40940582, 2025). "Thus, a key question remains how CIC::DUX4 sarcoma cells mechanistically repair DNA under CCNE1-mediated high replicative stress states prior to mitotic entry?" (PMID 40760094, 2025). "Thus, we now link components of the cell-cycle and DNA replication and repair pathways that are frequently observed to be dysregulated in CIC::DUX4 sarcomas." (PMID 40760094, 2025). "Abnormal expression of DUX4 has been observed in sarcoma and hematologic malignancies, which indicates that DUX4 may function as an oncogene." (PMID 40427614, 2025). "Notably, using RNA-seq, we observed that POLE was significantly downregulated following CIC::DUX4 suppression in CIC::DUX4 fusion sarcoma cells, and gene ontology analysis further indicated that POLE was associated with DNA damage and repair pathways." (PMID 40760094, 2025). "Interestingly, when CIC::DUX4 was expressed in non-sarcoma cell lines (HEK293T, C2C12, and NIH-3T3), POLE expression remained unaffected, suggesting a cell-context specific response." (PMID 40760094, 2025). "Leveraging biological insight of how WT DUX4 (and CIC::DUX4) interacts with p300, they rationalized that p300 inhibition could potentially overcome CIC::DUX4 sarcoma growth and survival." (PMID 38882060, 2024). "In order to prevent the accumulation of DNA damage in S phase and to subsequently prevent premature mitotic entry, CIC::DUX4 sarcomas depend on the G2/M checkpoint kinase WEE1 to delay mitotic entry and to ensure proper DNA repair and integrity prior to mitosis." (PMID 38882060, 2024). "Thus, RNAi-based technologies and/or cell penetrating antibodies that can effectively target the DUX4 in the context of the CIC::DUX4 fusion can open another therapeutic avenue directed at selective targeting of the CIC::DUX4 oncoprotein in human sarcoma." (PMID 38882060, 2024). "It will be also interesting to investigate whether DUX4 similarly mediates HLA class I silencing in CIC::DUX4 gene fusion positive sarcomas." (PMID 38318504, 2023). "CIC-DUX4 sarcoma (CDS) is a highly aggressive and metastatic small round type of predominantly pediatric sarcoma driven by a fusion oncoprotein comprising the transcriptional repressor Capicua (CIC) fused to the C-terminal transcriptional activation domain of DUX4." (PMID 34642317, 2021).
sarcoma (continued). "However, these regions could be clinically significant, such as the DUX4 region, which is involved in CIC::DUX4 fusion-positive sarcomas." (PMID 40041857, 2025). "CIC::DUX4 sarcoma (CDS) is a lethal cancer driven by a fusion between tumor suppressor Capicua (CIC) and pioneer transcription factor double homeobox 4 (DUX4)." (PMID 41279843, 2025). "In these sarcomas, the transcriptional repressor CIC is fused to the double homeobox transcription factor DUX4 or to the homologue DUX4L10, or in rare cases, to FOXO4 or NUTM1." (PMID 38611033, 2024). "Biopsy revealed a primitive round cell sarcoma with positive nuclear expression of DUX4 and WT1, suggestive of a CIC-rearranged sarcoma." (PMID 38436779, 2024). "The translocation of the DUX4 C-terminus transforms CIC from a transcriptional repressor to an activator, thereby driving the development of CIC::DUX4 sarcoma." (PMID 39367409, 2024). "Multiple mouse models of CIC::DUX4-driven sarcoma have been recently developed, each with spontaneous CIC::DUX4 expression." (PMID 38916046, 2024). "A recent addition to the family is the double homeobox 4 (DUX4) protein, which is of specific interest for sarcoma pathobiology." (PMID 36741019, 2023). "CIC-rearranged sarcoma is a high-grade undifferentiated round cell sarcoma defined by CIC-related gene fusions, most often CIC::DUX4." (PMID 36983010, 2023). "In contrast to CIC::DUX4 rearranged round cell sarcomas, BCOR::CCNB3 rearranged sarcomas are more inclined to occur in the bone, whereas CIC rearrangement sarcomas tend to develop in soft tissues and to follow a more aggressive trajectory." (PMID 38170001, 2023). "CIC sarcoma represents a new entity harboring the recurrent chromosomal translocation between CIC and, in most of the cases, DUX4." (PMID 36358827, 2022). "In this review, we focus on the Capicua transcriptional repressor (CIC)-double homeobox 4 gene (DUX4) sarcoma (CDS), a high-grade sarcoma with poor outcome." (PMID 36358827, 2022). "All CIC‐rearranged sarcomas have a fusion of CIC transcriptional repressor with various partners, most often DUX4, but also NUTM1 or NUTM2 have been observed." (PMID 35266242, 2022). "In sarcomas, the fusion between CIC and DUX4 leads to the transformation of CIC from transcriptional repressor to transcriptional activator, with the consequent upregulation of its target genes such as PEA3 genes." (PMID 36358827, 2022). "The fusion gene partners in CIS-rearranged sarcomas are most commonly DUX4 and DUX4L and less commonly FOX04." (PMID 33801953, 2021). "For these reasons, we nominated POLE as a key CIC::DUX4 target gene that could potentially regulate DNA repair and replication in CIC::DUX4 sarcomas." (PMID 40760094, 2025). "To evaluate the SplitFusion algorithm in detecting highly repetitive genes, we used two clinical sarcoma cases (Massachesetts General Hospital [MGH] case #1 and case #2) with confirmed CIC::DUX4 fusion, detected using a clinically validated assay based on AMP targeted RNA-seq." (PMID 40041857, 2025). "CDS is an aggressive sarcoma, which is driven by a neomorphic transcriptional activator, CIC::DUX4." (PMID 41279843, 2025). "CIC-rearranged sarcomas are rare, high-grade, undifferentiated, small round cell sarcomas of bone and soft tissue classified by gene fusions involving the CIC gene with other gene partners, most commonly the DUX4 gene." (PMID 40599504, 2025). "Moreover, they identify that CIC::DUX4 transcriptionally upregulates DUSP6 to silence ERK activity and sustain CIC::DUX4 oncoprotein expression in sarcoma." (PMID 38882060, 2024).
sarcoma (continued). "Through deep mechanistic dissection of CIC::DUX4 biology we and others have identified preclinical targets that warrant clinical validation to refine the treatment paradigm for patients with CIC-rearranged sarcoma." (PMID 38882060, 2024). "Beyond directly shaping output, partner gene domains can also determine regulation of the fusion, as is the case for ERK-mediated degradation of capicua (CIC)::double homeobox 4 (DUX4; CIC-rearranged sarcoma) due to retention of the CIC ERK-binding domain in the fusion oncoprotein." (PMID 39530749, 2024). "Recently, DUX4 immunostaining has been reported to be diffusely positive in all cases of CIC rearranged sarcomas evaluated (5/5 cases), but negative among other SBRCTs, including ES." (PMID 32155762, 2020). "Moreover, CIC fusion to non-DUX4 genes such as FOXO4, NUTM1, and NUTM2A seems to lead to histology and features similar to those with CIC-DUX4, although CIC-LEUTX sarcomas are related to CD31 and ETS-related gene expression." (PMID 31676869, 2019). "In this study, they included CIC::DUX4, BCOR-altered, EWSR1::ATF1/CREB1, and YWHAE::NUTM2B sarcomas, as well as fusion-negative SRCSs, reflecting the expanding molecular landscape within this spectrum." (PMID 41514642, 2025). "While CIC-rearranged sarcomas tend to be positive for CD99, WT1, ETV4, and DUX4, these stains are fairly nonspecific and are not sensitive enough to be used alone, thus, there remains a need for specialized genetic testing such as RNA sequencing or RT-PCR for confirmatory diagnosis." (PMID 40599504, 2025). "The absence of myogenic markers helped to exclude alveolar rhabdomyosarcoma, while ‘next‐generation immunohistochemistry’, which exploits the molecular genetics of mesenchymal neoplasms, including SS18‐SSX and DUX4, helped to rule out synovial sarcoma and CIC‐rearranged sarcomas, respectively." (PMID 40640075, 2025). "The C1 domain is retained in the fusion transcripts of the few existing patient-derived CIC::DUX4 sarcoma cell lines, but there has been no large-scale comprehensive analysis of CIC::DUX4 patient fusion breakpoints and which functional domains are retained in their fusion oncoproteins." (PMID 39530749, 2024).
Facioscapulohumeral dystrophy (25 papers, 2013 to 2025). Facioscapulohumeral muscular dystrophy (FSHD) is characterized by progressive muscle weakness with focal involvement of the facial, shoulder and limb muscles. "Loss of epigenetic repression can result in the aberrant expression of DUX4 in skeletal muscle and can cause facioscapulohumeral dystrophy (FSHD)." (PMID 40627547, 2025). "Facioscapulohumeral Dystrophy (FSHD) is caused by aberrant expression of the DUX4 gene which is normally silenced in skeletal muscle." (PMID 40558510, 2025). "Mis-expression of DUX4 in skeletal muscle causes facioscapulohumeral dystrophy (FSHD), whereas expression in cancers suppresses IFNγ induction of major histocompatibility complex class I (MHC class I) and contributes to immune evasion." (PMID 37092726, 2023). "Facioscapulohumeral dystrophy (FSHD) is a muscle disease caused by inappropriate expression of the double homeobox 4 (DUX4) gene in skeletal muscle, and its downstream activation of pro-apoptotic transcriptional programs." (PMID 37893058, 2023). "Facioscapulohumeral dystrophy (FSHD) is a skeletal muscle disease caused by the aberrant expression of the DUX4 gene in the muscle tissue." (PMID 35910413, 2022). "Aberrant DUX4 expression is associated with facioscapulohumeral dystrophy (FSHD), while DUX4 rearrangements have been also identified in Ewing-like sarcoma and rhabdomyosarcoma." (PMID 34501239, 2021). "Facioscapulohumeral dystrophy (FSHD) is caused by the mis-expression of DUX4 in skeletal muscle cells." (PMID 28273136, 2017). "Facioscapulohumeral dystrophy (FSHD) is a progressive muscular dystrophy caused by mis-expression of the double-homeobox transcription factor DUX4 in skeletal muscle." (PMID 28273136, 2017). "DUX4 has additionally been identified as the causal gene in facioscapulohumeral dystrophy (FSHD), leading to the protein being intensely studied to identify its pathological traits." (PMID 37034731, 2023). "Despite the awareness of DUX4 expression in normal germline biology, DUX4 is principally described as a toxic factor involved in facioscapulohumeral dystrophy (FSHD) pathophysiology." (PMID 32731450, 2020). "DUX4, which is known to be associated with facioscapulohumeral dystrophy (FSHD), activates a large portion of the genes normally expressed at the onset of ZGA, particularly including cleavage-specific genes that have an upstream enriched binding motif for DUX4." (PMID 30759824, 2019). "Facioscapulohumeral dystrophy (FSHD) is a progressive muscle disease caused by mutations that lead to epigenetic derepression and inappropriate transcription of the double homeobox 4 (DUX4) gene in skeletal muscle." (PMID 28870238, 2017). "As DUX4 is studied in more detail in a disease called facioscapulohumeral dystrophy (FSHD), knowledge on treatment strategies could be gained from this disease." (PMID 32630675, 2020). "Furthermore, the LTR of MaLR family THE1D is activated by transcription factor DUX4 which is specifically expressed in facioscapulohumeral dystrophy, implying involvement of DUX4 in the pathophysiology." (PMID 24062987, 2013). "To test the therapeutic potential of adenine base editing in facioscapulohumeral dystrophy, we targeted the DUX4 polyadenylation signal and achieved efficient DUX4 mRNA downregulation in FSHD muscle cell cultures." (PMID 34484861, 2021). "Facioscapulohumeral dystrophy (FSHD) is a progressive muscular dystrophy caused by decreased epigenetic repression of the D4Z4 macrosatellite repeats and ectopic expression of DUX4, a retrogene encoding a germline transcription factor encoded in each repeat." (PMID 23593020, 2013). "DUX4 is the major gene responsible for facioscapulohumeral dystrophy (FSHD)." (PMID 39518930, 2024). "Facioscapulohumeral dystrophy (FSHD) is a muscular dystrophy resulting from an altered contraction on chromosome 4 and disrupted methylation allowing for DUX4 transcription." (PMID 35749388, 2022).
Facioscapulohumeral dystrophy (continued). "While in normal adult organism the role of DUX4 is unknown and might be limited to germline, the role of DUX4 in pathology (i.e. in Facioscapulohumeral dystrophy or FSHD) has been extensively explored." (PMID 27556182, 2016). "Since aberrant expression of DUX4 was identified as a major factor in the etiology of facioscapulohumeral dystrophy (FSHD), several therapeutic approaches were developed to inhibit its expression in this context and could be potentially useful to treat DUX4-rearranged ALL." (PMID 33255367, 2020). "Further analyses including the functional analyses of DUX4, PAX3 and PAX7 in ECs could improve our understanding of a vascular pathogenesis in DUX4-related diseases, particularly in the contexts of cancer and facioscapulohumeral dystrophy." (PMID 40965075, 2025). "Facioscapulohumeral dystrophy (FSHD) is characterized by the contraction of the D4Z4 array located in the sub-telomeric region of the chromosome 4, leading to the aberrant expression of the DUX4 transcription factor and the mis-regulation of hundreds of genes." (PMID 29751519, 2018).